ATOX1 (antioxidant 1 copper chaperone)
Diseases named in the same sentence as ATOX1 in open-access papers (continued):
Sharing a sentence is not in itself a finding about the gene and the disease.
multiple myeloma (2 papers, 2025). "In multiple myeloma (MM), our previous transcriptomic analysis revealed significantly higher ATOX1 expression in extramedullary multiple myeloma (EMM) patients compared to those with bone-marrow-confined MM." (PMID 40002764, 2025). "Further research is necessary to delineate the role of ATOX1 in cancer cell migration, as the ATOX1-ATP7A-LOX axis and copper metabolism pathways were recently identified as COMM domain-containing protein 3 (COMMD3)-regulated signaling cascades involved in the progression of multiple myeloma." (PMID 40721800, 2025).
non-small cell lung carcinoma (2 papers, 2016 to 2024). A group of at least three distinct histological types of lung cancer, including non-small cell squamous cell carcinoma, adenocarcinoma, and large cell carcinoma. "ATOX1 inhibition reduced copper-stimulated cell proliferation in mouse embryonic fibroblasts and non-small cell lung cancer cells." (PMID 27206673, 2016).
ulcerative colitis (2 papers, 2024 to 2025). An inflammatory bowel disease involving the mucosal surface of the large intestine and rectum. "A previous study has implicated the Atox1 gene in the causation of ulcerative colitis." (PMID 38796413, 2024). "Future studies should also investigate the in vivo role of nuclear Atox1 in other IBD animal models such as dextran sodium sulfate-induced ulcerative colitis." (PMID 38796413, 2024). "Moreover, in a study, Atox1 expression was found to be higher in active ulcerative colitis samples, was negatively correlated with CD8+ T cell infiltration, and showed excellent diagnostic value for ulcerative colitis." (PMID 38796413, 2024).
acute myeloid leukemia (1 paper, 2026). Acute myeloid leukemia (AML) is a group of neoplasms arising from precursor cells committed to the myeloid cell-line differentiation. "Although the copper chaperone human antioxidant protein 1 (ATOX1) plays a key role in cuproptosis, its link to acute myeloid leukemia (AML) progression remains unclear." (PMID 41615715, 2026).
and neck cancer (1 paper, 2022). "Consistently, small molecules targeting Atox1 have been proved to effectively block Cu-trafficking and consequently reduce cell proliferation in lung, leukemia, breast, head, and neck cancer cell lines by elevating cellular ROS levels via Cu accumulation and reducing cellular NADPH and GSH levels." (PMID 36299299, 2022). "Moreover, inhibiting Atox1 delivery to CCS protein by small molecules was effective in killing breast, lung, leukaemia, head, and neck cancer cells in vitro and in a mouse xenograft model, while having only minimal effects on healthy cells." (PMID 36299299, 2022).
Arthritis (1 paper, 2025). Inflammation of a joint. "The SOD3, CAT, GPX and ATOX1 genes were expressed at substantially lower levels in arthritis-affected rams." (PMID 40005882, 2025). "The expression of the SOD3, CAT, GPX and ATOX1 genes was significantly reduced in the rams with arthritis." (PMID 40005882, 2025). "The rams suffering from arthritis exhibited abnormally low levels of gene expression for SOD3, CAT, GPX and ATOX1." (PMID 40005882, 2025). "This research described the antioxidant (SOD3, CAT, GPX, ATOX1 and COX18) and immunological (IL-1α, IL-1β, IL-6, IL-10, TNFα, NCF4, NFKB, TMED, FCAMR and iNOS) genes in rams that had arthritis and those that did not." (PMID 40005882, 2025).
bladder cancer (1 paper, 2024). "Drugs targeting ATOX1 (e.g., cisplatin) have been approved for the treatment of metastatic ovarian tumors, metastatic testicular tumors, and advanced bladder cancer." (PMID 39284832, 2024).
cerebral amyloid angiopathy (1 paper, 2025). "One further possibility is that ATOX1 leads to a significant decrease in AD cases with cerebral amyloid angiopathy present as a comorbidity, while this study specifically looks at AD-only diagnoses." (PMID 40149738, 2025).
cognitive deficits (1 paper, 2025). "Experimental evidence suggests that overexpression of the copper chaperone antioxidant 1 (Atox1) provides neuroprotection against TBI-induced cognitive deficits by DJ- 1-dependent antioxidative pathways and enhancing mitophagy." (PMID 40237948, 2025).
colitis (1 paper, 2024). Inflammation of the colon. "We then detected the effects of Atox1 on inflammation in TNBS-induced colitis using mice homozygous for the conditional Atox1 allele (Atox1−/−); WT mice were used as control." (PMID 38796413, 2024). "Macrophages isolated from TNBS-induced colitis mice showed M1 polarization and nuclear translocation of Atox1." (PMID 38796413, 2024). "Atox1 expression was up-regulated in colon tissues of TNBS-induced colitis mice." (PMID 38796413, 2024). "We report Atox1 up-regulation in colon tissues of TNBS-induced colitis mice models." (PMID 38796413, 2024). "Moreover, macrophages isolated from the intestinal mucosa of TNBS-induced colitis mice showed upregulation of Atox1 nuclear translocation and a decrease in Cu content." (PMID 38796413, 2024). "Our results showed that the Atox1 protein expression was increased while Cu content was decreased in colonic tissues and macrophages of TNBS-induced colitis mice." (PMID 38796413, 2024). "Inhibition of Atox1 activity with DCAC50 inhibited CuCl2-induced p47phox expression and macrophage M1 polarization and the therapeutic effects of Atox1 knockout in TNBS-induced mice, suggesting the involvement of copper chaperone-induced Cu trafficking in TNBS-induced colitis." (PMID 38796413, 2024).
concussion (1 paper, 2021). A concussion, also known as a mild traumatic brain injury (mTBI), is a head injury that temporarily affects brain functioning. "Combining three of the protein biomarkers (ATOX1, SPARC and NT5C3A), produced an AUC of 0.98 for concussion diagnoses (P < 0.001; 95% CI: 0.95, 1.00)." (PMID 34987469, 2021).
Crohn disease (1 paper, 2024). A gastrointestinal disorder characterized by chronic inflammation involving all layers of the intestinal wall, noncaseating granulomas affecting the intestinal wall and regional lymph nodes, and transmural fibrosis. "Atox1 expression in macrophages was elevated in the inflamed areas compared to the uninflamed area of the colon in patients with Crohn’s disease." (PMID 38796413, 2024). "Similarly, our study demonstrated the upregulation of Atox1 in patients with Crohn’s disease and the TNBS-induced mouse model of Crohn’s disease." (PMID 38796413, 2024). "However, the effects of Atox1-mediated inflammation in the progression of Crohn’s disease and the underlying mechanisms are not well characterized." (PMID 38796413, 2024). "First, we did not verify Atox1 expression levels in clinical specimens from patients with Crohn’s disease and only performed bioinformatics analysis of clinical data." (PMID 38796413, 2024).
dengue (1 paper, 2016). "Our meta-analysis data have identified a previously unnoticed oxidative stress responsive gene ATOX1 (Antioxidant protein 1) during DENV infection, which is significantly upregulated across all the dengue patients PBMC data sets." (PMID 27651116, 2016).
esophageal cancer (1 paper, 2024). A primary or metastatic malignant neoplasm involving the esophagus. "Among them, the genes CTSZ, CTSC, DAD, COLEC12, ATOX1, etc., in the TUBA1B+Mac-C0 cluster have a causal relationship with esophageal cancer." (PMID 38434988, 2024). "Genes causally associated with the occurrence of esophageal cancer are identified within the AGG cluster, including CTSZ, CTSC, DAD, COLEC12, ATOX1, etc., offering new evidence for clinical immune therapy." (PMID 38434988, 2024). "Mendelian randomization analysis revealed a causal relationship between genes such as CTSZ, CTSC, DAD, COLEC12, ATOX1, within the AGG cluster, and the onset of esophageal cancer." (PMID 38434988, 2024). "The Mendelian randomization results indicate a causal relationship between genes such as CTSZ, CTSC, DAD1, COLEC12, ATOX1 in the TUBA1B+Mac-C0 cluster and the occurrence of esophageal cancer." (PMID 38434988, 2024).
invasive ductal carcinoma (1 paper, 2010). "From the immunohistochemistry studies, increased expression from matched normal to DCIS (ductal carcinoma in situ) and IDC (invasive ductal carcinoma) were observed for AK1 (8/21 or 38% of all cases) and ATOX1 (10/19 or 53% of all cases)." (PMID 20543960, 2010).
lung adenocarcinoma (1 paper, 2025). A carcinoma that arises from the lung and is characterized by the presence of malignant glandular epithelial cells. "In this study, based on publicly available proteomic data of lung adenocarcinoma (LUAD), we used bioinformatics analysis, in vitro cellular experiments, and in vivo animal experiments to deeply investigate the functions and potential therapeutic strategies of ATOX1 and ROCK1 in LUAD." (PMID 40940984, 2025).
mastitis (1 paper, 2025). Inflammation of breast tissue during lactation or postpartum due to an obstructed duct or infection. "Mastitis-affected sheep had significantly reduced expression levels of the genes CAT, GPX1, ATOX1, GST, and Nrf2 compared to resistant ewes." (PMID 40542007, 2025). "In the current investigation, qRT-PCR was used to measure the levels of antioxidant (CAT, GPX1, Keap1, OXSR1, ATOX1, GST, and Nrf2) and immune (IFN-γ, IL-4, TNF-α, MYD88, CCL5, TLR4, TLR9, LTF, and PRLR) genes in Barki ewes that were resistant and non-resistant to mastitis." (PMID 40542007, 2025).
Menkes disease (1 paper, 2016). A usually severe multisystemic disorder of copper metabolism, characterized by progressive neurodegeneration and marked connective tissue anomalies as well as typical sparse abnormal steely hair. "Although no disease mutations have been reported in ATOX1, Menkes disease like phenotype was observed in ATOX1 knockout mice." (PMID 27401861, 2016).
metastatic colorectal cancer (1 paper, 2020). "Our findings suggest that nuclear Atox1 might be a new therapeutic target as well as a new biomarker for metastatic colorectal cancer." (PMID 31961892, 2020).
pancreatic adenocarcinoma (1 paper, 2025). "This analysis confirmed that ATOX1 mRNA levels are generally increased in the cancers with the most significant upregulation in DLBC, liver hepatocellular carcinoma, ovarian serous cystadenocarcinoma, skin cutaneous melanoma, pancreatic adenocarcinoma, thymoma, and uterine carcinosarcoma." (PMID 40721800, 2025). "Furthermore, the knockdown of ATOX1, but not CCS, significantly increased the sensitivity of pancreatic adenocarcinoma cells to the genotoxic drugs gemcitabine and adriamycin." (PMID 40721800, 2025).
peripheral vascular disease (1 paper, 2015). Any disorder affecting blood flow through the veins or arteries outside of the heart. "In this study, we show that Atox1 expression is significantly upregulated in mice and patients with CLI, supporting the clinical significance of Atox1 in peripheral vascular disease." (PMID 26437801, 2015).
prostate carcinoma (1 paper, 2022). A carcinoma that arises from epithelial cells of the prostate gland. "Interestingly, we found high expression of antioxidant genes; SOD1, TXN, LAMTOR5, and ATOX1 in prostate cancer patients having higher ERG fusion expression." (PMID 35508713, 2022).
Sepsis (1 paper, 2025). Sepsis is defined as life-threatening organ dysfunction caused by a dysregulated host response to infection. "The expression of SLC31A1, CD274, ATOX1, MTF1, UBE2D1, DLD, and VEGFA was found to be upregulated, while that of DLST, UBE2D2, COX11, DLAT, GLS, FDX1, and ULK2 were significantly downregulated in patients with sepsis-associated ALI." (PMID 38779731, 2025).
skin cancer (1 paper, 2020). "ATOX1, which donates copper ions to SOD3, seems to have a cell line-dependent expression that is especially high in skin cancer cell lines (it is unclear if it is skin cancer cell-specific or also observed in normal skin cells)." (PMID 32756515, 2020).
skin cutaneous melanoma (1 paper, 2019). "In terms of somatic copy-number alterations, Atox1 is subjected to a deletion process in a high percentage of skin cutaneous melanoma (SKCM) samples (8.7%), while the deletion percentage, for either gene, could not exceed the 5% value for all the remaining 13 cancers studied." (PMID 31575544, 2019).
triple-negative breast carcinoma (1 paper, 2021). An invasive breast carcinoma which is negative for expression of estrogen receptor (ER), progesterone receptor (PR), and human epidermal growth factor receptor 2 (HER2). "Our results show that higher ATOX1 levels in the tumor cell cytoplasm correlate with a trend towards better event-free survival after TM treatment for triple-negative breast cancer patients and patients at stage III of disease." (PMID 34944703, 2021).
uterine corpus endometrial carcinoma (1 paper, 2019). A endometrial carcinoma (disease) that involves the body of uterus. "It seems that neither the Atox1 nor CCS gene are often mutated in any of the cancers examined, with the highest mutation frequency for CCS and Atox1 observed in uterine corpus endometrial carcinoma (UCEC) (1.5%) and liver hepatocellular carcinoma (LIHC) (0.27%) malignancies, respectively." (PMID 31575544, 2019).
cancer (41 papers, 2010 to 2025). A tumor composed of atypical neoplastic, often pleomorphic cells that invade other tissues. "ATOX1 has been implicated in cancer biology because of its role in the proliferation and metastatic spread of cancer cells and protection from oxidative stress." (PMID 40721800, 2025). "In turn, the role of ATOX1 in the susceptibility of cancer cells to targeted therapies and immunotherapy remains elusive." (PMID 40721800, 2025). "The multifaceted actions of ATOX1 indicate that its dysregulation can lead to changes in the activity of crucial signaling pathways associated with diverse disorders, including cancer." (PMID 40721800, 2025). "In this respect, owing to its metallochaperone and transcription-associated activities, the contribution of ATOX1 to multiple cancer-related processes is related to the regulation of the functions of several cancer cell-associated proteins." (PMID 40721800, 2025). "ATOX1-mediated dysregulation of copper homeostasis is associated with increased oxidative stress and altered cellular behavior, potentially leading to cancer development." (PMID 39036924, 2024). "Many copper-binding proteins associated with cancer have been identified, such as antioxidant-1 (Atox1), which is involved in the cell cycle, cell proliferation, angiogenesis, and vascular remodeling." (PMID 38305803, 2024). "The ATOX1 copper trafficking protein is linked to reduced proliferation of cancer cells demonstrated by knockout experiments of its gene." (PMID 29258235, 2017). "In this respect, ATOX1 is also closely associated with several features of cancer development and progression, including uncontrolled cell proliferation, angiogenesis, stimulation of invasion and metastatic spread, disruption of cellular metabolic processes and drug resistance." (PMID 40721800, 2025). "Hence, before applying a cisplatin-dependent regimen to a cancer patient, the thorough mutational and expression profiling of (among others) Atox1 and CCS genes are strongly advised." (PMID 31575544, 2019). "In a recent study, we showed that peptides that interact with Atox1 and MBD 3/4 units of ATP7B affect copper metabolism in breast and liver cancer cells and cause preferential toxicity in cancer cells." (PMID 41463392, 2025). "Our research discovers that two specific proteins in cancer cells—one that handles copper (ATOX1) and another that controls cell movement (ROCK1)—work together to drive cancer growth." (PMID 40940984, 2025). "Since many types of cancer are characterized by increased levels of intratumoral copper, ATOX1-dependent regulation of the phenotype of cancer cells can be largely associated with the protumorigenic role of copper known as cuproplasia." (PMID 40721800, 2025). "Key copper metal chaperones, such as Antioxidant Protein 1 (ATOX1), promote cell migration in various cancers, including breast cancer." (PMID 40002764, 2025). "The upregulation of ATOX1 in several cancers and its involvement in inflammatory vascularization make ATOX1 a potential therapeutic target (for a recent review, see Ref." (PMID 39172219, 2025). "In turn, no significant decrease in cell proliferation was observed in normal human keratinocytes upon ATOX1 knockdown suggesting that ATOX1 can be particularly crucial for the proliferation of cancer cells." (PMID 40721800, 2025). "The results reported here agree with a growing list of studies suggesting that variable ATOX1 regulation and activities contribute to tissue differentiation, development, and cancer." (PMID 40672323, 2025). "In this review, we comprehensively discuss the molecular aspects of ATOX1 as well as its key interactions with distinct molecules crucial for cancer development and progression, and highlight the potential clinical relevance of targeting ATOX1 in cancer." (PMID 40721800, 2025).